MUC2 (mucin 2, oligomeric mucus/gel-forming)
Diseases named in the same sentence as MUC2 in open-access papers (continued):
Sharing a sentence is not in itself a finding about the gene and the disease.
gastric cancer (continued). "KRTHB3 (basic keratin 3), MUC2 (mucin 2), and PCOLN3 (type III procollagen N-endopeptidase) all have altered expression in EBV-associated gastric carcinomas." (PMID 16448567, 2006). "MUC1 and MUC2 are already well known to be overexpressed in gastric cancers, however, MUC13, a transmembrane mucin, might play an as-yet-unknown role in cell signaling and epithelial barrier protection." (PMID 39910169, 2025). "We demonstrated that MUC2 expression is also regulated by DNA methylation in stomach cancer." (PMID 33947930, 2021). "In addition to these risk factors, we also recently demonstrated that genetic variability in specific genes (e.g., MUC2, NFKB1 and CD14) is associated with the progression to gastric cancer from precursor lesions." (PMID 34199386, 2021). "MUC2 is an important marker for gastric cancer and intestinal metaplasia." (PMID 27277677, 2016). "They reported that Cdx1 and Cdx2 expression was independent of the type of IM and of gastric carcinoma, and that it was significantly associated with expression of the intestinal mucin Muc2." (PMID 19412438, 2007). "The role of CDX2 in gastric cancer has been reported as responsible for the proliferation and differentiation of intestinal type of epithelial cells by controlling transcriptional activation of intestine specific proteins, like sucrase-isomaltase, carbonic anhydrase I, or Mucin 2 (MUC2)." (PMID 29867026, 2018). "Therefore, MUC2 expression might be inversely correlated with tumour aggressiveness in gastric carcinomas." (PMID 15354218, 2004). "The gastric cancer markers CK7 (-), TTF-1 (-), and NapsinA (-) completely exclude lung derived metastasis, while Muc-2 (+), Muc-5AC (+), and Muc-6 (+) are gastric mucinous phenotypes, indicating gastric primordia." (PMID 40837582, 2025). "Other established target genes of CDX2, such as MUC2, are upregulated by CDX2 in gastric cancers, as confirmed previously and herein." (PMID 39768557, 2024). "The mucin expression profile of GOJc was mixed, containing high MUC2 gene expression consistent with oesophageal and high MUC6 gene expression consistent with gastric cancers." (PMID 37958425, 2023). "In the resected gastric cancer tissues, mucin expression rates were 71.4% for MUC1, 78.6% for MUC2, 75.4% for MUC5AC, and 33.3% for MUC6." (PMID 36831343, 2023). "The expression of MUC5AC, MUC6, MUC2, and CD10 was shown in 346 (52.7%), 425 (64.7%), 149 (22.7%), and 176 (26.8%) of the 657 early differentiated gastric cancer lesions, respectively." (PMID 36977979, 2023). "Meanwhile, REG4 expression was significantly associated with both the intestinal mucin phenotype (mucin 2 [MUC2] and CDX2) and neuroendocrine differentiation of gastric cancer." (PMID 36172286, 2022). "This article reviews the diagnostic and prognostic values of molecular markers in complete (MUC2) and incomplete (MUC2, MUC5AC, and MUC6) intestinal metaplasia, gastric dysplasia/intra-epithelial neoplasia, and early gastric cancer." (PMID 34206291, 2021). "As KLF4 deletion induced MUC2 expression in the mouse antrum and KLF4 levels are decreased in human gastric cancer, we analyzed MUC2 expression in a preliminary study using 11 gastric cancer samples provided by NanFang Hospital." (PMID 27277677, 2016). "In this study we characterized the expression of the transcription factor SOX2 in gastric cancer and related it with clinicopathological features and differentiation markers namely MUC5AC (gastric marker) and CDX2 and MUC2 (intestinal markers)." (PMID 25300947, 2014). "CDX2 promotes MUC2 expression but is not always co-expressed; CDX2-negative/MUC2-positive gastric cancers have been reported, indicating this finding can occur in MUC2-positive gastric tumors." (PMID 39939466, 2025). "MUC2 expression decreases during metaplasia from normal gastric mucosa to intestinal-type, whereas MUC5AC is upregulated with more aggressive gastric tumours, and MUC6 is downregulated in gastric cancer." (PMID 37958425, 2023).
gastric cancer (continued). "To further examine the correlation between KLF4 and MUC2 in human gastric cancer, and to understand the clinical relevance of these two proteins, we purchased TMA slides composed of 81 tumor samples and 8 normal tissues from the gastric cancer patients." (PMID 27277677, 2016). "Muc2, an intestinal type of mucin, was ectopically expressed in the gastric mucosa only of HFD-fed mice, indicating that gastric mucin was converted to the intestinal type as has been observed in most human gastric carcinomas." (PMID 26839577, 2016). "Normal gastric mucosa show little or no expression of MUC2, but gastric carcinoma mucosa exhibit a heterogeneous mucin expression pattern." (PMID 18000536, 2007). "It remains to be investigated whether all mucins (MUC1, MUC2, MUC4, MUC 5AC, MUC 5B, MUC6 etc.) may carry these sialylated and sulfated oligosaccharidic sidechains detected in intestinal metaplasia, gastric carcinoma and cholelithiasis." (PMID 17565665, 2007). "Our present findings show that the gastric and intestinal phenotypic marker expression of the tumour, determined by immunohistochemical staining for HGM, MUC6, MUC2 and CD10, can be used to predict the pattern of gastric carcinoma recurrence after curative resection." (PMID 15354218, 2004). "MUC2, an intestinal phenotype mucin gene with no expression in normal gastric mucosa, is upregulated via the NFΚB signaling pathway in both gastric IM and gastric carcinoma." (PMID 37240039, 2023). "The gastric carcinoma markers MUC2, MUC5AC, and MUC6 were expressed weakly or not at all." (PMID 31367188, 2019). "However, we did not see any change in MUC2 expression, suggesting that KLF4 does not directly control MUC2 transcription in gastric cancer cells." (PMID 27277677, 2016). "Several authors have reported that gastric carcinomas can be classified as having either a gastric (G), gastric and intestinal mixed (GI) or intestinal (I) phenotype, depending on the immunopositivity of human gastric mucin (HGM), MUC6, MUC2 and CD10 stainings." (PMID 15354218, 2004). "In conclusion, our present findings show that the gastric and intestinal phenotypic marker expression of the tumour, determined by the HGM, MUC6, MUC2 and CD10 expression patterns, may be used to predict the recurrence pattern of gastric carcinomas after curative resections." (PMID 15354218, 2004). "Most of the other colorectal and gastric cancer markers such as CDX2, MUC1, MUC2, and MUC6 were also negative." (PMID 34397857, 2021).
ulcerative colitis (43 papers, 2006 to 2025). An inflammatory bowel disease involving the mucosal surface of the large intestine and rectum. "In this report, we investigated the role of the gut microbiome using Winnie mice, an ulcerative colitis–like (UC-like) model with a missense mutation in the Muc2 gene." (PMID 41196658, 2025). "Previous histological observations in ulcerative colitis patients have indeed associated a depletion of goblet cells and mucus secretion with decreased MUC2 synthesis and secretion in the colonic epithelium." (PMID 36707815, 2023). "In mice deficient in Muc2, colonic inflammation and superficial erosions are seen that mimic ulcerative colitis as early as 5 weeks old." (PMID 36900282, 2023). "Evidence shows a decrease in the thickness of adherent mucus layer during ulcerative colitis that is linked to genetic changes of MUC-2, the most abundant mucin protein in the intestine." (PMID 33842393, 2021). "Evidence shows a decrease in mucus layer thickness during ulcerative colitis that is linked to changes in the genes responsible for MUC-2 expression, the most abundant mucin found in the intestine." (PMID 32824269, 2020). "In patients with severe ulcerative colitis an absolute deficiency of expression of MUC2 and MUC3 in goblet cells were observed in 100% of patients, indicating the most pronounced changes in the synthesis and secretion of mucins in patients with severe UC." (PMID 23737764, 2013). "In conclusion, our results show that HPE treatment was effective in attenuating most of the damage caused by DSS‐induced ulcerative colitis, as evidenced by the improvements in the morphological parameters assessed and the restoration of MUC‐2 expression in goblet cells." (PMID 41165567, 2025). "HPE effectively attenuated DSS‐induced colon damage and restored MUC‐2 expression, contributing to epithelial barrier restoration and supporting its therapeutic potential in ulcerative colitis." (PMID 41165567, 2025). "DSS‐induced ulcerative colitis significantly reduced MUC‐2 expression in the colonic goblet cells of the colon compared to the control group (p < 0.05)." (PMID 41165567, 2025). "(C, D) Representative co-immunofluorescence images of human ulcerative colitis (UC) and control colon biopsy sections stained for Rab7 (red) and Muc2 (green) for goblet cells (marked with asterisk) (scale bar = 50 μm)." (PMID 38593125, 2024). "Alterations in O-glycans on MUC2 have been observed in ulcerative colitis (UC), which refers to an increase in the number of truncated O-glycans Tn antigen, STn antigen, and a decrease in the number of complex O-glycans on MUC2." (PMID 37894512, 2023). "MUC2 is the most vital component of the mucus layer and its expression level is reduced in ulcerative colitis." (PMID 37576825, 2023). "Although MUC5AC is expressed at low levels in the gastrointestinal tract and upregulated in pathological conditions such as ulcerative colitis or parasitic infection, under physiological conditions colonic goblet cells secrete MUC2." (PMID 30272559, 2018). "Recently, we demonstrated that spontaneous intestinal inflammation in Muc2-/- mice is restricted to the colon and shares features of human ulcerative colitis." (PMID 26121642, 2015). "Previous studies have shown that decreased number of goblet cells and reduced Muc2 expression is commonly observed in ulcerative colitis and colorectal carcinoma." (PMID 24941171, 2014). "Altered O-glycosylation of MUC2 mucins have also been shown to occur in sigmoid biopsies from patients with active ulcerative colitis." (PMID 23977158, 2013). "A change in post-transcriptional processing of MUC2 has been noted in inflamed colonic mucosa from patients with Crohn's disease or ulcerative colitis." (PMID 16504136, 2006).
ulcerative colitis (continued). "IELs and mast cells play a central role in the immunopathology of ulcerative colitis and the observed restoration of MUC‐2 expression suggests that HPE also contributed to the restoration of goblet cell secretory barrier function, which is essential for mucosal homeostasis." (PMID 41165567, 2025). "A. mucilyticum, newly isolated from ulcerative colitis patients and rarely present in healthy individuals, degrades mucins such as MUC2 by secreting various types of mucin O-glycans-targeting CAZymes, and utilizes the released monosaccharides as substrates for colonization and proliferation." (PMID 41300441, 2025). "Interestingly, IIMs that have been described thus far share many similarities with MUC2, one of the core components of mucus in the human intestine and a key player in the pathogenesis of ulcerative colitis." (PMID 38558941, 2024). "Finally, to determine if fecal MUC2 O-glycans can be used to detect differences in Ulcerative Colitis (UC) samples, we obtained feces from control and UC patients (n = 3) and extracted MUC2." (PMID 38272223, 2024). "Winnie, a mouse carrying a missense mutation in the MUC2 mucin gene, is a valuable model for inflammatory bowel disease (IBD) with signs and symptoms that have multiple similarities with those observed in patients with ulcerative colitis." (PMID 35732858, 2022). "We also investigated whether the role of MUC2 differs between children and adults, ulcerative colitis (UC) and Crohn's disease (CD)." (PMID 35602503, 2022). "Because human ulcerative colitis proceeds proximally from rectum to cecum, we hypothesized that infiltration of neutrophils in Muc2-/- mice would be more prominent in the distal than the proximal colon." (PMID 26121642, 2015). "Furthermore, its expression is decreased in patients with ulcerative colitis and collective data supports a model in which Muc2 is essential for the protection of the intestinal epithelium against commensal bacteria and potential pathogens in mice." (PMID 23776483, 2013). "A reduction in total MUC2 secretion also seems evident in active ulcerative colitis." (PMID 21152122, 2010). "Treatment with RJ improved symptoms and colonic cell apoptosis and decreased intestinal permeability by increasing the expression of tight-junction protein, goblet cells and their secretion mucin, MUC2, in DSS-induced ulcerative colitis mice." (PMID 35631210, 2022). "Here, we have shown that MUC2/Muc2 has the potential to induce pro-inflammatory responses, inducing IL-8 expression and DC activation in human moDCs, which may be important in the context of different inflammatory conditions such as Crohn's disease and ulcerative colitis." (PMID 29581231, 2018). "The aim of the study was to analyze expression of mucins (MUC2, MUC3, and MUC4) and trefoil factor-3 (TFF3) and its influence on colon mucosal barrier in patients with ulcerative colitis and Crohn's disease." (PMID 23737764, 2013). "As expected, the VK2 administration substantially alleviated the ulcerative colitis, and it was mainly by decreasing the DAI index, increasing the expression of anti-inflammatory factor IL-10, muc2, and tight junction proteins (ZO-1, occludin), and by improving the intestinal tissue architecture." (PMID 36769323, 2023). "The Muc2 gene expression is reduced or absent in patients with Crohn’s disease, whereas Muc2 production and secretion are decreased in active ulcerative colitis, resulting in a thin mucus layer and increased intestinal absorption." (PMID 37835487, 2023). "To assess if the phenomenon we observed in human LS174T goblet-like cells was true of more complex and relevant diseases, the expression of MUC2/FCGBP was determined from human biopsy samples taken from healthy controls and patients with active ulcerative colitis (UC) and UC in remission (UC-R)." (PMID 37359538, 2023).
ulcerative colitis (continued). "Concurrently, MUC2 mutant mice (Winnie) develop spontaneous inflammation that mimic ulcerative colitis due to accumulation of non-functional mucin glycoprotein." (PMID 33182355, 2020). "Within the same study, unglycosylated MUC2 precursors were also noted to occur in human ulcerative colitis, even in noninflamed intestinal tissue." (PMID 21152122, 2010). "Alterations or absence of MUC2 production can lead to many common human disorders such as colon carcinoma, ulcerative colitis, and celiac disease." (PMID 20138044, 2010).
mucinous adenocarcinoma (41 papers, 2007 to 2026). An invasive adenocarcinoma composed of malignant glandular cells which contain intracytoplasmic mucin. "Although decreased MUC2 expression is associated with colorectal adenocarcinoma, its expression is always maintained in mucinous carcinomas." (PMID 36900282, 2023). "MUC2 has been shown to be expressed in normal colonic tissue, while its decreased expression is associated with non-mucinous colon adenocarcinomas." (PMID 36900282, 2023). "In the current study, MUC2 expression was associated with mucinous carcinoma, consistent with a previous report, and with superficial invasion depth, negative venous invasion, and curative resection, but not with a better prognosis in appendiceal carcinoma." (PMID 25551773, 2014). "Conversely, MUC2 overexpression has been recognized as a hallmark of mucinous adenocarcinoma (MAC)." (PMID 40142267, 2025). "Although MUC2 overexpression was specifically associated with mucinous carcinoma, its effects on tumor progression remain unclear." (PMID 25322805, 2014). "Our coupled MS approach reveals a striking mucin 2 (MUC2) expression pattern in three colorectal mucinous adenocarcinomas, in which different glycoforms clearly stratify regions within each tumor." (PMID 42098121, 2026). "Some study pointed out that MUC2 showed higher expression rate in diffuse type carcinomas, especially in mucinous carcinomas." (PMID 39886661, 2024). "Mucinous adenocarcinoma (a more aggressive LC subtype) showed higher expression of secretory mucins, including MUC2, MUC5AC, and MUC6." (PMID 36980526, 2023). "Our experimental results showed that MUC2 was strongly expressed in all the cases and was significantly higher than that in the peripheral invasive ductal carcinoma, lobular carcinoma, or mucinous carcinoma." (PMID 37337182, 2023). "Low frequency of MUC2 expression was also demonstrated in another study (only in one of 25 invasive mucinous adenocarcinomas)." (PMID 36367122, 2023). "MUC2 was strongly expressed in all the cases and was significantly enhanced compared with peripheral invasive ductal carcinoma, lobular carcinoma, or mucinous carcinoma." (PMID 37337182, 2023). "On the other hand, the IPNB pathway, which frequently progresses to colloid adenocarcinoma, is characterized by a positive expression of MUC2, indicating the MUC2-positive pathways." (PMID 37721561, 2023). "These mucinous carcinomas are generally characterized by changes in MUC2 expression, both in terms of glycosylation and in levels of secretion." (PMID 35933341, 2022). "With regard to the mucus phenotype of each lesion, the IAPN was MUC2 and MUC5AC positive, while the mucinous adenocarcinoma was MUC2-positive and MUC5AC-negative." (PMID 33452648, 2021). "Mucinous adenocarcinoma, accounting for 10–15% of CRCs, is characterized by distinct molecular and clinicopathological features, including MUC2 overexpression, microsatellite instability (MSI), and multiple metastases." (PMID 34300195, 2021). "In almost all cases, colloid carcinoma develops from pre-existing intraductal papillary mucinous neoplasms, especially those forming intestinal-type papillae, and is characterized by MUC2 expression, which is rarely found in pancreatic ductal carcinoma." (PMID 34487254, 2021). "MUC2 was included because mucinous adenocarcinoma in CRC has been shown to have a better prognosis than adenocarcinoma in general." (PMID 32049988, 2020).